FSTL3 (follistatin like 3)
Diseases named in the same sentence as FSTL3 in open-access papers (continued):
Sharing a sentence is not in itself a finding about the gene and the disease.
tumor (continued). "In summary, the high expression of FSTL3 can lead to anti-PD1 therapy resistance, and the combination with IDO1 inhibitor can sensitize the therapy for a better anti-tumor effect." (PMID 38302412, 2024). "Pairwise analysis revealed that tumor tissues exhibited significantly elevated expression of KRT81, KRT6A, KRT17, and KRT14, which were positively correlated with FSTL3 expression, compared to that in normal tissues." (PMID 38240936, 2024). "We found that the expression levels of EFEMP2, EHD2, FSTL3 and ALOX5 were decreased in tumor tissues, whereas COL3A1 was significantly increased in tumor samples." (PMID 37291533, 2023). "Seven hub genes (AXL, EFEMP2, VIM, EHD2, FSTL3, ALOX5, HSPB8) were downregulated in tumor samples, while COL3A1 was upregulated in tumor samples in the TCGA dataset." (PMID 37291533, 2023). "Based on the comparison of the solid tissue normal and primary tumour groups, it appeared that the FSTL family and FSTL3 exhibited significant differences (p < 0.0001)." (PMID 36807490, 2023). "TIMP1, PGF, FSTL3, SNAI1, and FOXC1 were highly expressed in CAFs with high stemness scores in the tumor intestinal tissues." (PMID 37017587, 2023). "The expression of FSTL3 was a significant prognostic marker in multivariate analysis of DSS, along with tumour T status and distal metastasis." (PMID 36807490, 2023). "Based on TCGA-LIHC, there was high expression of FSTL3 and PKM in the HCC tumor samples compared with the controls (P < 0.05)." (PMID 38044354, 2023). "Following transfection of tumor tissues from mice with shLBX2-AS1, western blotting results showed that the protein levels of FSTL3, vimentin, N-cadherin, MMP2, and MMP9 decreased." (PMID 36325361, 2022). "Six tumor antigens (THBS2, FSTL3, TNNT1, BGN, CTHRC1, and NOX4) were identified as potential therapeutic candidates for the anti-CRC mRNA vaccine that can be processed and presented by APCs to activate a robust immune response." (PMID 35127707, 2021). "qRT-PCR, western blot, and IHC determined FSTL3 expression in RCC tissues and the compared non-tumor tissues." (PMID 34555811, 2021). "Hematoxylin-eosin staining of tumor sections suggested a more irregular cell shape and packing in tumors from the parent cell line MGC-803-derived tumor compared to FSTL3 knockdown conditions." (PMID 34425560, 2021). "At least one of the inhibitors GPC3, GREM1, FSTL3, and/or FST were over-expressed (FC > 1.5) in 100% of tumor samples." (PMID 23667740, 2012). "Meanwhile, according to the analysis of correlation between the level of FSTL3 expression and clinicopathological characteristics in clinical specimens, those patients with high FSTL3 expression were in more advanced T, N, M and TNM stages, with a larger tumor diameter." (PMID 38302412, 2024). "In addition, FSTL3-mediated β-catenin pathway activation promoted CRC aerobic glycolysis, thereby affecting tumor invasion and metastasis ability." (PMID 37957183, 2023). "Moreover, the expressions of TIMP1, PGF, FSTL3, SNAI1, and FOXC1 were significantly up‐regulated in the tumor tissues." (PMID 37017587, 2023). "Taken collectively, these findings suggest that FSTL3 and LAMC1 are involved in tumor biology and targeting LINC00922 may be an effective therapy in GC patients." (PMID 35511773, 2022). "In the same study, FSTL3 overexpression increased the expression of proteins involved in aerobic glycolysis, such as GLUT1, LDHA, HK2, and PKM2, resulting in a decrease in the pH of the tumor microenvironment and contributing to tumor cell immune evasion." (PMID 36325361, 2022). "The immunohistochemistry images indicated low- or negative expression levels of FSTL3 in the paired normal tissues (NT) and high-expression in tumor (T), metastatic lymph node (LN), and IVE tissues." (PMID 34395416, 2021).
tumor (continued). "Western blot showed that the protein expression levels of FSTL3, Vimentin, N-cadherin, MMP2 and MMP-9 in the mice tumor tissue in the sh-LBX2-AS1 experimental group were decreased, indicating that FSTL3 expression was increased at protein level and EMT was promoted." (PMID 34858481, 2021). "In conclusion, this study suggests a role for FSTL3 as a prognostic marker and as therapeutic target in HGSOC, where it may play a role in promoting a mesenchymal tumor phenotype, maintaining an immunosuppressive tumor microenvironment, and driving immunotherapy resistance." (PMID 41029436, 2025). "In cancer cells, FSTL3 prevented the ubiquitination and degradation of c-Myc through interaction with c-Myc, triggered the transcriptional expression of downstream PDL1 and IDO1, and thus blocked the anti-tumor effect of CD8+ T cells and enhanced the infiltration of Tregs." (PMID 38302412, 2024). "It remains unclear how alterations in FSTL3 may lead to tumour progression, and its role in the tumorigenesis of CRC is not well understood." (PMID 36807490, 2023). "Therefore, we investigated whether the expression of THBS2, FSTL3, TNNT1, BGN, CTHRC1, and NOX4 was correlated with immune cell infiltration levels in CRC via the Tumor Immune Estimation Resource (TIMER) database." (PMID 35127707, 2021). "Among the genes that showed a negative correlation with FSTL3 expression, SNORD17, SNORA23, SCARNA6, and SNORD15B exhibited significantly increased expression in tumor tissues compared to that in normal tissues." (PMID 38240936, 2024). "Our data illustrated that abundant FSTL3 expression is a negative prognosticator in CRC patients (n = 130), and is significantly correlated with lymph node metastasis, staging, tumor size and IVE." (PMID 34395416, 2021). "Although there was no single tumor marker, we identified a set of genes (Bone Morphogenetic Protein inhibitors GPC3, GREM1, FSTL3, and FST) in which at least one gene was over-expressed in 100% of the tumor samples." (PMID 23667740, 2012).
cancer (27 papers, 2017 to 2025). A tumor composed of atypical neoplastic, often pleomorphic cells that invade other tissues. "High expression level of FSTL3 is closely associated with the strong abilities of migration and invasion of cancer cells." (PMID 36325361, 2022). "Underlying these processes, cancer cells overexpressing FSTL3 exhibited increased expression of the genes associated with epithelial-mesenchymal transition (Vim, Zeb-1, Snai1/2) and extracellular matrix organization (Ecm1), while expression of epithelial markers (Epcam, Cdh1) decreased." (PMID 41029436, 2025). "FSTL3 is an independent risk factor connected with the prognosis for different cancers." (PMID 36251702, 2022). "The analysis results showed that the FSTL3 expression was more positively associated with abundances of TIICs such as cancer-associated fibroblasts (CAFs), macrophages (M1- and M2-like), myeloid dendritic cell and CD4+/CD8+ cells, whereas it was negatively associated with B cells and NK cells." (PMID 34335633, 2021). "FSTL3 is an independent risk factor and is linked with poor prognosis within various cancers." (PMID 34395416, 2021). "However, recent studies implicated FSTL3 in the regulation of a range of cancers." (PMID 34425560, 2021). "In contrast, activin A (Inhba), one of the main ligands bound by both FST and FSTL3 was primarily secreted by cancer cells, while its type II receptors (Acvr2a, Acvr2b) were highly expressed in both cancer cells and fibroblasts (Log2 FC > 0.5)." (PMID 41029436, 2025). "We next investigated the spatial pattern of expression of FST/FSTL3 to understand the relative contributions of cancer cells and stromal cells to their secretion in the TME." (PMID 41029436, 2025). "Dot plot analysis demonstrated that FST and FSTL3 were expressed in stromal cell populations of cancer-associated mesothelial cells (CAMC) and cancer-associated fibroblasts (CAF), at a higher level than in cancer cells." (PMID 41029436, 2025). "In the present study, it is found out that FSTL3 is not only hyper-expressed in cancer cells of CRC but also correlated with immune evasion." (PMID 38302412, 2024). "According to the analytical results, the level of FSTL3 protein expression was higher in the cancer tissues than in the normal tissues, and the hyperexpression of FSTL3 occurred predominantly in the nucleus." (PMID 38302412, 2024). "In comparison with the matched normal samples, the cancer tissues in the TCGA CRC cohort exhibited higher levels of FSTL3 expression." (PMID 38302412, 2024). "According to previous literature reports, high expression of SNAI1 can promote the invasion ability of cancer cells, low expression of FRMD5 can weaken the metastatic ability of cancer cells, and low expression of FSTL3 also has similar functions." (PMID 36925652, 2023). "Gene ontology previously implicated FSTL3 in a wide variety of signalling pathways associated with epithelial–mesenchymal transition (EMT), including the signalling pathway involved in cancer metastasis." (PMID 36807490, 2023). "Considering that there has been an explosive growth in research on PKM in cancer, we further focus on FSTL3 and confirmed the abnormal expression of FSTL3 in two independent validations set (P < 0.0001)." (PMID 38044354, 2023). "Eighty‐two of the 236 cancer samples stained cytologically positive for FSTL3 (34%), while 60 of 236 cancer samples stained positively for nuclear FSTL3 (25%)." (PMID 36807490, 2023). "In total, nine inflammation and cancer-associated DEGs were selected to show their changed expression patterns, comprising four up-DEGs (ADM, FSTL3, SPDEF, and SPNS2) and five down-DEGs (TACSTD2, CCL2, EDIL3, FAM20C, and OLFML2A)." (PMID 37953789, 2023). "Using cancer bioinformatics, we found that FSTL3 expression is elevated in a large majority of the 33 cancers we analyzed in publicly available cancer databases." (PMID 34425560, 2021).
cancer (continued). "To assess the correlation between miR-486-5p, FSTL3 and cancer status, we used the STAD database within TCGA." (PMID 34425560, 2021). "Subsequent studies have progressively corroborated that FSTL3 makes a great contribution to cancer development." (PMID 34555811, 2021). "In this study, we used cancer bioinformatics to evaluate FSTL3 levels in different cancers in the TCGA database." (PMID 34425560, 2021). "We found that FSTL3 expression levels were correlated with TMB among multiple types of cancers, including BRCA, CHOL, LGG, LIHC, LUSC, PCPG, and THYM, but not CRC." (PMID 34335633, 2021). "To further confirm the guidance value of FSTL3 for individualized therapy, we conducted a pan-cancer analysis." (PMID 34335633, 2021). "Meanwhile, FSTL3 mRNA expression level in cancer tissues was also higher than that in normal tissues (P = 2.1e-09)." (PMID 34335633, 2021). "Follistatin-like 3 (FSTL3), which mediates cell differentiation and growth, acts as a biomarker of tumors and participates in cancer development and progression." (PMID 34555811, 2021). "Furthermore, the IF analysis of CRC tissues revealed that a significant FSTL3 expression was shown by KRT19-positive cancer cells." (PMID 38302412, 2024). "In the present study, it is revealed that FSTL3 is hyper-expressed in cancer cells of CRC." (PMID 38302412, 2024). "Thus, we constructed a co-culture model of FSTL3-OE CRC cells with CD8+ T cells to explore the effect of FSTL3 in cancer cells on CD8+ T cells." (PMID 38302412, 2024). "In the subsequent cell activity and apoptosis experiments, we found that the low expression of SNAI1, CDR2L, FRMD5, and FSTL3 could reduce the activity of cancer cells and increase the apoptosis rate of cancer cells." (PMID 36925652, 2023). "Studies about the regulatory mechanism and function of FSTL3 may provide new therapeutic strategies for cancer and other pathologies." (PMID 36325361, 2022). "NcRNAs were found to regulate the expression of FSTL3, thereby affecting cancer cell genesis." (PMID 36325361, 2022). "Recent studies have reported substantial overexpression of FSTL3 in a subset of cancers." (PMID 36245988, 2022). "Such overexpression of FSTL3 may promote proliferation and metastasis in this type of cancer, while knockdown of FSTL3 plays the opposite role." (PMID 34440203, 2021). "In addition, we found that FSTL3 expression level was significantly correlated with the expression of immune checkpoint molecules in the vast majority of cancers." (PMID 34335633, 2021). "FSTL3 expression was profiled in clinical datasets for 33 cancers deposited in the TCGA database." (PMID 34425560, 2021). "In the group with high FSTL3 expression, macrophage recruitment and inflammatory immune cell infiltration activity were noticeably enhanced, while CD8+ T cell recruitment and cancer cell killing activity were reduced." (PMID 38302412, 2024). "We observed at the pan-cancer level that the expression pattern of FSTL3 and PKM varied greatly among different cancer types." (PMID 38044354, 2023). "Firstly, we evaluated the relationship between FSTL3 and TMB and MSI among multiple types of cancers, which were both regarded as independent predictors of immunotherapy efficacy." (PMID 34335633, 2021). "Additionally, the significant correlation of FSTL3 and IVE also reflects the intense invasive ability of cancer cells and is therefore considered as a potential predictor of metastasis." (PMID 34395416, 2021). "FSTL3 expression varied in cancer tissues, ranging from no staining to strong cytoplasmic staining." (PMID 36807490, 2023). "A uniquely enriched pathway of all five PCGs (FSTL3, KLF6, MLF1, NR4A3, and SDC4) was “Transcriptional misregulation in cancer” (P = 0.048), suggesting that those five PCGs and their regulating lncRNAs may play roles in transcriptional regulation levels in THCA." (PMID 29340074, 2017).
metabolic disease (2 papers, 2021 to 2022). A congenital disorder (due to inherited enzyme abnormality) or acquired (due to failure of a metabolically important organ) disorder resulting from an abnormal metabolic process. "Besides, the level of FSTL3 expression itself can act as a diagnostic biomarker reflecting the dynamics of bone tissue formation in healthy people and patients with metabolic disorders." (PMID 34440203, 2021). "Firstly, FSTL3 is one of our most intriguing findings, in part, because of its emerging role in metabolic diseases." (PMID 35323665, 2022).
renal disease (2 papers, 2018 to 2023). "There has not been investigation of MDK or FSTL3 in other subset of SSc patients who might have increased concentrations of those specific proteins, such as patients with cardiac involvement or renal disease." (PMID 30115106, 2018).
blood disorders (1 paper, 2021). "FSTL3 was originally discovered as a rearranged gene locus associated with some blood disorders and malignancies." (PMID 34425560, 2021).
cardiovascular diseases (1 paper, 2025). "Diet-associated proteins (e.g., FSTL3, STC1, and CD302 antigen) significantly mediate risk associations for various chronic disorders, including cardiovascular diseases and chronic respiratory diseases." (PMID 40823023, 2025).
immune dysfunction (1 paper, 2025). "This hypothesis suggests that immune dysfunction associated with FABP4, CDR2, and FSTL3 may play a crucial role in the co-morbid development of T2DM and CRC." (PMID 40595026, 2025).
FSTL3 also shares sentences with these, for which no sentence is quoted: lung fibrosis (4 papers); acute myocardial infarction (2); osteoporosis (2); type 2 diabetes (2); allergic asthma (1); allergic disease (1); astrocytoma (1); atrial fibrillation (1); B-cell chronic lymphocytic leukemia (1); breast diseases (1); breast tumor (1); choriocarcinoma (1); diffuse large B-cell lymphoma (1); ductal carcinoma in situ (1); endometrial carcinoma (1); endometriosis (1); gastric tumor (1); glaucoma (1); Glucose intolerance (1); Hepatic steatosis (1); Hyperglycemia (1); idiopathic pulmonary fibrosis (1); Impaired glucose tolerance (1); infection (1); Infertility (1); infiltrating ductal carcinomas (1); invasive carcinoma (1); Miscarriage (1); Myocardial fibrosis (1); ovarian endometriosis (1).
A further 2 diseases each share a sentence with FSTL3 in 1 paper.